CASP1 (caspase 1)
Diseases named in the same sentence as CASP1 in open-access papers (continued):
Sharing a sentence is not in itself a finding about the gene and the disease.
Fever (2 papers, 2010 to 2022). Body temperature elevated above the normal range. "GasderminD (GSDMD), in the inflammasome, activates CASP1, a member of the cysteinyl aspartate protease (caspase, or CASP) gene family to induce pyrexia." (PMID 35296025, 2022).
focal epilepsy (2 papers, 2022 to 2026). A seizure caused by a localized disorder. "VX-765 is a safe and effective inhibitor of caspase-1 that has been proved to be well tolerated in phase II clinical trial in patients with partial epilepsy." (PMID 35673561, 2022).
geographic atrophy (2 papers, 2013 to 2022). "In macular RPE tissue from donors with geographic atrophy that is associated with late AMD, an increase of NLRP3, ASC, Caspase-1, IL-1β, and IL-18 proteins was observed." (PMID 35805159, 2022). "Other reports investigating the role of inflammasome in the pathogenesis of AMD observed an increased content of NLRP3, ASC, Caspase-1, IL-1β, and IL-18 protein in RPE tissue from the macula region of donors with geographic atrophy (GA) compared to non-diseased controls." (PMID 35805159, 2022).
Gliosis (2 papers, 2018 to 2025). Gliosis is the focal proliferation of glial cells in the central nervous system. "Genetic ablation of caspase-1 function in wobbly mice not only reinforced the role of NLRP3 in the progression of neurodegeneration, but also identified caspase-1 as a potential therapeutic target in gliosis-associated ataxias in addition to NLRP3 itself." (PMID 30097576, 2018).
Heat Stroke (2 papers, 2018 to 2021). A condition caused by the failure of body to dissipate heat in an excessively hot environment or during PHYSICAL EXERTION in a hot environment. "Then, the hypothesis was confirmed by showing that either LPS or heat stroke alone failed to induce significant caspase-1 p10 or IL-1β maturation." (PMID 34092247, 2021).
Hydrocephalus (2 papers, 2023 to 2024). Hydrocephalus is an active distension of the ventricular system of the brain resulting from inadequate passage of CSF from its point of production within the cerebral ventricles to its point of absorption into the systemic circulation. "aSAH patients presented significantly higher levels of caspase-1, IL-18, and IL-1β in CSF for all timepoints when compared with hydrocephalus patient controls." (PMID 39195261, 2024). "In contrast, recent study reported that NLRP3 activity is increased in patients with delayed neurological injury or hydrocephalus by elevated caspase 1 in CSF." (PMID 35819747, 2023). "Despite the heterogenous control group, we demonstrate that aSAH patients had significantly higher levels of ASC, caspase-1, IL-18, and IL-1β up to 5 days post-injury when compared to hydrocephalus non-aSAH patient controls." (PMID 39195261, 2024).
hypopharyngeal carcinoma (2 papers, 2021 to 2022). Carcinoma, predominantly squamous cell, arising from the epithelial cells of the hypopharynx. "It is worth noting that the expression of caspase 1 in hypopharyngeal carcinoma tissue was negatively correlated with the expression of circCUX1 (r = -0.4643, p = 0.0003, N = 78)." (PMID 33741902, 2021). "We found that compared with normal tissues adjacent to cancer, caspase 1 was significantly reduced in hypopharyngeal cancer tissues, especially in radiotherapy-resistant tissues." (PMID 33741902, 2021).
intestinal tumors (2 papers, 2017 to 2022). "Our results show that PsV eradicates intestinal tumours of ApcMin/+ mice via activating the NLRP3 and AIM2 inflammasomes, leading to caspase-1-mediated tumour regression." (PMID 28397782, 2017). "CASP1 ablation in intestinal epithelial cells of mice has a protective response against inflammation-induced intestinal tumors compared to controls, independent of gut microbiota composition, suggesting an immune-deprived status under normal physiology upon downregulation." (PMID 36544093, 2022).
kidney stone (2 papers, 2024 to 2025). "Inhibiting CaOx crystal induced renal cell pyroptosis, including downregulating the expression of NLRP3, caspase-1, IL-1β, and other related pyroptosis proteins, can reduce the risk of kidney stone formation." (PMID 39768161, 2024).
lentivirus infection (2 papers, 2017 to 2021). Virus diseases caused by the Lentivirus genus. "Western blot confirmed the knockdown of NLPR3, ASC, and pro-caspase-1 at protein level 3 days after lentivirus infection." (PMID 33708197, 2021).
macrophage activation syndrome (2 papers, 2023 to 2025). A complication of rheumatic disease that is caused by excessive activation and uncontrolled proliferation of T lymphocytes and well-differentiated macrophages. "A novel finding by Jørgensen and colleagues (2020) identified an extremely rare heterozygous missense variant in the CASP1 gene encoding pro-caspase-1 in a patient with systemic JIA (sJIA) and recurrent macrophage activation syndrome (MAS)." (PMID 37598797, 2023).
migraine (2 papers, 2022 to 2023). "Neuroinflammation pathways, specifically those involving inflammasome proteins, such as IL-1β, IL-18, and caspase-1, seem promising candidates as biomarkers or treatment targets in migraine, providing some interesting direction for further study." (PMID 35896985, 2022).
Miscarriage (2 papers, 2024 to 2025). A pregnancy that ends at a stage in which the fetus is incapable of surviving on its own, defined as the spontaneous loss of a fetus before the 22th week of pregnancy. "The assessment of placental tissue samples revealed a statistically significant higher expression of IL-1β (p < 0.0001), IL-18 (p < 0.0001), and Caspase-1 (p < 0.0001) proteins in all women with miscarriage as compared to the control group." (PMID 39408839, 2024). "Placental tissues from women with miscarriage exhibited a high expression of Caspase-1 in 100% of cases and a weak expression in 100% of control women." (PMID 39408839, 2024). "In the placental tissue samples, a higher expression of IL-1β, IL-18, and Caspase-1 proteins was noted in women who had experienced miscarriage as compared to the control group." (PMID 39408839, 2024). "This hypothesis is supported by the high expression of IL-1β and IL-18, along with elevated levels of Caspase-1 in the placenta tissue of women who experienced miscarriage." (PMID 39408839, 2024).
mood disorder (2 papers, 2021 to 2024). A cognitive disorder a disturbance in which the person's mood is hypothesized to be the main underlying feature. "Overall, the studies report an increase in mRNA expression of NLRP3, ASC, and caspase-1 genes in mood disorder patient groups when compared to healthy controls." (PMID 34830395, 2021).
morbid obesity (2 papers, 2022). An excess of body weight, normally defined as an individual with a body mass index greater than 35 or a body weight greater than one hundred percent of ideal body weight. "Interestingly, plasma caspase-1 concentrations normalized in both groups, whereas plasma IL-1β levels normalized only in patients with morbid obesity and normal glucose tolerance suggesting the persistence of a systemic inflammatory condition in people with T2D." (PMID 36012889, 2022).
mycobacterial infection (2 papers, 2017 to 2025). "High IL-1β production and high mortality were unexpectedly found in M. tb-infected mice deficient in caspase-1 implicates the existence of caspase-1 independent IL-1β production in mycobacterial infection." (PMID 29228045, 2017). "NLRP3 inflammasomes are multiprotein complexes which play a fundamental role in the body’s immune response to mycobacterial infection by providing a platform for caspase-1 activation." (PMID 40142455, 2025).
nephrocalcinosis (2 papers, 2021). Nephrocalcinosis is a disorder that occurs when too much calcium is deposited in the kidneys. "To address the potential contribution of caspase 1 and NADPH oxidase 2 ﻿during nephrocalcinosis, we fed 129/B6J mice deficient in Casp1, Cybb and Casp1/Cybb an oxalate-rich diet, a previously characterized mouse model of CaOx crystal-induced nephropathy." (PMID 33968083, 2021). "Moreover, immunohistochemistry analysis revealed high expression levels of NLRP3, caspase-1, and IL-1β in nephrocalcinosis samples." (PMID 34512861, 2021). "Thus, the data indicate that unlike WT mice on a B6N background, Casp1-/-, Cybb-/- and Casp1/Cybb-/- mice on a 129/B6J background lack CaOx crystal deposition and related nephrocalcinosis." (PMID 33968083, 2021). "Indeed, Casp1-/-, Cybb-/- or Casp1-/-/Cybb-/- knockout mice on a 129/C57BL/6J (B6J) background that were fed an oxalate-rich diet for 14 days did neither encounter intrarenal CaOx crystal deposits nor nephrocalcinosis-related CKD." (PMID 33968083, 2021).
ocular hypertension (2 papers, 2019 to 2021). Abnormally high intraocular pressure. "To understand the underlying mechanism of PM2.5-related ocular hypertension, we measured the levels of proteins associated with the classic pyroptosis pathway (NLRP3/caspase-1/IL-1β/GSDMD) in aqueous humor outflow tissue." (PMID 33663554, 2021).
ovarian tumor (2 papers, 2020 to 2025). "The study objective was to determine if the NLRP3 inflammasome components (NLRP3, caspase-1), and the corresponding cytokine products, IL1β and IL18, were increased in ovarian tumors." (PMID 31923221, 2020). "Similar to the chicken, CASP1 (2.7x; p = 0.05), IL1β (4.9x; p = 0.04) and IL18 (33x; p = 0.02) mRNA were significantly higher in human ovarian tumors." (PMID 31923221, 2020). "The Human Protein Atlas suggests human ovarian tumors express NLRP3, caspase-1, IL1β and IL18." (PMID 31923221, 2020).
Pain (2 papers, 2015 to 2022). An unpleasant sensory and emotional experience associated with actual or potential tissue damage, or described in terms of such damage. "Meanwhile, the synthesis of caspase-1 in DRG of SNL rats is also increased, suggesting that activation of caspase-1 in peripheral nervous system is the pathophysiological basis for pronociceptive hypersensitivity in chronic neuropathic pain." (PMID 35592413, 2022). "Importantly, we have recently used these methods to suggest a role for the inflammasome (including elevated IL-18 and caspase-1) in a rat model of chronic neuropathic pain." (PMID 26635801, 2015).
papilloma (2 papers, 2014 to 2022). A benign epithelial neoplasm that projects above the surrounding epithelial surface and consists of villous or arborescent outgrowths of fibrovascular stroma. "Macroscopically visible papillomas were detected at the 5th week of TPA application on CASP-1-KO, at the 7th week on ASC-KO, and only at the 10th week on WT mice." (PMID 25268644, 2014). "All ASC-KO mice developed visible papilloma by the 10th week after carcinogenic induction while all CASP-1-KO mice developed papilloma by the 18th week." (PMID 25268644, 2014). "In the DMBA/TPA model of skin carcinogenesis, expression of IL-1RI, caspase-1, NLRP3, and ASC—the latter in myeloid cells—supports the incidence of papillomas." (PMID 36293159, 2022). "Absence of ASC and CASP-1 resulted in an earlier incidence and increased number of papilloma." (PMID 25268644, 2014).
parasite (2 papers, 2014 to 2018). "ASC-/- and caspase-1-/- mice have been doCumented to exhibit a higher incidence of mortality, cardiac parasitism and heart inflammation, meaning that ASC/caspase-1 inflammasomes are critical determinants of host resistance to infection with T. cruzi." (PMID 25372293, 2014). "THP-1 cells that lacked caspase-1 or NLRP3 were severely defective in IL-1β production in the parasite infections." (PMID 30301855, 2018).
peripheral arterial disease (2 papers, 2020 to 2022). A disorder of the arteries supplying the upper and lower extremity and the visceral organs. "In studies involving the plasma of patients with peripheral arterial diseases, the stimuli of cholesterol crystals in the HAEC can activate the intracellular NLR receptors of endothelium signals in the macrophages and trigger caspase-1 activation through cellular response." (PMID 35528818, 2022).
proliferative diabetic retinopathy (2 papers, 2018 to 2020). Advanced retinopathy due to diabetes mellitus characterized by the formation of new vessels in the retina. "In line with our results also other groups identified elevated levels of IL-1ß and its activator molecule caspase-1 in vitreous of patients with proliferative diabetic retinopathy." (PMID 29584759, 2018).
prostate tumor (2 papers, 2017). "Prostate tumors with strong CYP1B1 expression showed low CASP1 levels." (PMID 28388569, 2017).
retinal ischemia (2 papers, 2016 to 2023). A ischemic disease that involves the retina. "This conclusion was made despite our data indicating the key roles of CASP1 and GSDMD in RGC death, which are typically associated with pyroptotic death in the retinal ischemia model." (PMID 37998361, 2023). "A recent study showed that inhibition of caspase-1 reduced IL-1β expression to baseline post retinal ischemia injury, while inhibition of caspase-8 further down-regulated the level of IL-1β, suggesting that IL levels could be regulated by both NLRP3-dependent and other pathways." (PMID 26893104, 2016). "Protection via the inhibition of Casp1 or other inflammasome-signaling proteins could suggest that RGC death in this model occurred via pyroptosis, like in the retinal ischemia–reperfusion model." (PMID 37998361, 2023).
rosacea (2 papers, 2017 to 2024). A chronic erythematous skin disorder that affects the face. "Pro-inflammatory cytokines such as interleukin (IL)-1 β, IL-6, IL-8, and tumor necrosis factor-α are involved in rosacea pathogenesis, and inflammasome-related genes (CASP-1 and NALP-3) are overexpressed in skin samples from rosacea patients." (PMID 28968402, 2017).
Rotavirus infection (2 papers, 2019 to 2024). Infection with any of the rotaviruses. "Nlrp9b−/− mice, and mice selectively deficient in caspase-1 in epithelial cells, but not Il18−/− mice, were highly susceptible to rotavirus infection, in terms of exaggerated diarrhea." (PMID 30717382, 2019).
sarcoidosis (2 papers, 2020 to 2023). Sarcoidosis is a multisystemic disorder of unknown cause characterized by the formation of immune granulomas in involved organs. "Both previously-found and novel cell death genes were enriched in Treg (e.g., BCL2, CASP1), substantiating the observation that sarcoidosis Treg have decreased survival." (PMID 33363531, 2020).
sarcopenia (2 papers, 2024 to 2026). Progressive decline in muscle mass due to aging which results in decreased functional capacity of muscles. "In summary, we present evidence for the involvement of the NLRP3/ASC/NEK7/Caspase-1 inflammasome pathway with activation of pro-inflammatory SASP in the outcome of sarcopenia in the elderly." (PMID 38338718, 2024).
SARS-CoV infection (2 papers, 2018 to 2020). "In summary, Rip3-mediated oligomerization of SARS 3a causes necrotic cell death, lysosomal damage, and caspase-1 activation—all likely contributing to the clinical manifestations of SARS-CoV infection." (PMID 30185776, 2018).
shigellosis (2 papers, 2020 to 2023). Shigellosis is a bacterial infection leading to dysentery and is caused by Shigella, which are small, ubiquitous Gram-negative bacteria belonging to the enterobacteria family. "Casp1/11/8–/–Ripk3–/– mice, however, are hyper-susceptible to shigellosis, indicating that programmed cell death is a predominant host defense mechanism against Shigella infection." (PMID 36645406, 2023). "All Casp1/11/8–/–Ripk3–/– mice presented with blood in their feces and one of the ten mice also died of shigellosis within 2 days of infection." (PMID 36645406, 2023). "We find that Casp1/11/8–/–Ripk3–/– mice, which lack the pathways to execute pyroptosis, extrinsic apoptosis, and necroptosis, experience severe shigellosis with a 500-fold increase in colonization of the intestinal epithelium relative to B6 WT mice." (PMID 36645406, 2023). "However, the susceptibility of B6 NAIP–NLRC4-deficient (but CASP11+) mice, as well as the resistance of Casp1/11–/– mice, suggest that these inflammasomes are not strictly redundant and that NAIP–NLRC4 alone is sufficient to confer resistance to shigellosis in mice." (PMID 33074100, 2020).
subarachnoid hemorrhage (2 papers, 2022 to 2023). A serious neurological disorder characterized by intracranial hemorrhage into the subarachnoid space. "Furthermore, fluoxetine mitigates NLRP3 inflammasome and caspase-1 activation through autophagy activation after subarachnoid hemorrhage (SAH) to treat early brain injury." (PMID 35810159, 2022). "For instance, MLT was also demonstrated to protect against brain damage induced by subarachnoid hemorrhage (SAH) via the suppression of NLRP3 inflammasome-related components, including ASC, cleaved Casp-1, IL-1β, and IL-669,70." (PMID 36747075, 2023).
systemic sclerosis (2 papers, 2022 to 2024). A chronic disorder, possibly autoimmune, marked by excessive production of collagen which results in hardening and thickening of body tissues. "For instance, in dermal fibroblasts from patients with systemic sclerosis, the inhibition of CASP1 reduces the collagen deposition and the IL-18 and IL-1β release." (PMID 38786058, 2024). "To reach this objective, we evaluated the presence of caspase-1, lactate dehydrogenase (LDH), the cytokines IL-1β and IL-18, and the association between them in the bronchoalveolar lavage (BAL) of patients with ASSD and systemic sclerosis (SSc)." (PMID 36611853, 2022).
tularemia (2 papers, 2016). Tularemia is an infection caused by the bacterium Francisella tularensis. "However, TNF-/-, IL-6-/- and Casp1/11-/- mice are more susceptible to pulmonary tularemia and, demonstrating the essential role of these cytokines in tularemia." (PMID 27015566, 2016). "Collectively, these data suggest that Nlrp3-dependent, but Asc, caspase-1/11, and caspase-3-independent cell death, which is likely necrosis/necroptotic, contributes to death of lung myeloid and epithelial cells during pulmonary tularemia." (PMID 27926940, 2016). "Intriguingly, severe necrosis during pulmonary tularemia requires Nlrp3, but appears largely independent of caspase-1 and Asc in both myeloid and lung epithelial cells." (PMID 27926940, 2016).
ulcer (2 papers, 2020 to 2025). "In uninfected ulcer patients, NLRP3 expression correlated with IL-1β, whereas in infected groups, active caspase-1 was closely associated with both GSDMD-N and mature IL-18, supporting canonical pyroptosis activation." (PMID 40563885, 2025). "Similarly, active caspase-1 and GSDMD-N levels were found to be significantly correlated in H. pylori-infected ulcer patients." (PMID 40563885, 2025).
urinary tract infection (2 papers, 2019 to 2022). "The inflammasome-associated proteins caspase-1, caspase-4 and NLRP3 have been emphasised to be vital in the host response during urinary tract infection by regulating IL-1β release." (PMID 35132157, 2022). "The inflammasome-associated proteins caspase-1, caspase-4 and NLRP3 have been emphasised to be essential in the host cell response during urinary tract infection (UTI) by regulating IL-1β release." (PMID 35132157, 2022).
Ventricular arrhythmia (2 papers, 2016 to 2025). "In the future, the expression of ASC, caspase-1 and IL-18 in the myocardium of ventricular arrhythmia rats will continue to increase, providing a theoretical basis for the resistance of cinnamaldehyde against myocardial inflammatory injury." (PMID 40146271, 2025). "In the absence of TLR2, NLRP3, Caspase 1 or IL-1r, DM fails to sensitize rodents to ventricular arrhythmias." (PMID 27882934, 2016).
Acute hepatitis (1 paper, 2025). Acute hepatic injury resulting from inflammation typically accompanied by increased serum alanine transaminase activity. "CA nanoparticles have also demonstrated the ability to reduce inflammation and apoptosis in acute hepatitis models by decreasing levels of TNF-α, IL-1β, and IL-18, as well as inhibiting NF-κB, NLRP3, and caspase-1, while promoting Bcl-2 levels." (PMID 40869259, 2025).